MUSK (muscle associated receptor tyrosine kinase)
Diseases named in the same sentence as MUSK in open-access papers (continued):
Sharing a sentence is not in itself a finding about the gene and the disease.
Myositis (2 papers, 2019 to 2022). "Myositis specific autoantibodies including Jo-1, ARS, MDA5, TiF1γ, Mi-2, Ku, PL-7, PL-10, OJ, EJ, HMGCR, SRP and myasthenic gravis related antibodies including anti AChR and MuSK antibody were negative." (PMID 31382909, 2019). "Anti-PM-Scl 75 and anti-signal recognition particle (SRP) antibodies were positive, but no other myositis specific autoantibodies, including Jo-1, ARS, MDA5, TiF1γ, Mi-2, Ku, PL-7, PL-10, OJ, EJ, or MG-related antibodies, including AChR and muscle specific kinase (MuSK) were observed." (PMID 31382909, 2019).
Respiratory insufficiency (2 papers, 2019 to 2024). "The patient had respiratory insufficiency, which is not commonly seen in the GFPT1 mutation; it is usually associated with mutations of RAPSYN, COLQ, MUSK, and others." (PMID 39559672, 2024).
Stroke (2 papers, 2020 to 2023). Sudden impairment of blood flow to a part of the brain due to occlusion or rupture of an artery to the brain. "Specifically, Shroom3 is involved in the Shroom3-Rho kinase signaling complex and is shown to inhibit axonal outgrowth and stroke recovery; MuSK gene encodes for MuSK tyrosine kinase, which is crucial for NMJ maintenance." (PMID 32629989, 2020). "Sspo, Shroom3, MuSK, Chrna2, Sorbs2, and Coro6 were upregulated in response to stroke." (PMID 32629989, 2020). "A recent RNAseq study of the TA muscle using a mouse stroke model in 5 m mice found altered transcriptomes compared to age-matched non-stroke mice including: an upregulation in stroke mice >log2fc1 of Gadd45a, Shroom3, Chrna2, and MuSK, along with downregulation (log2fc < −1) of P2ry1." (PMID 37876943, 2023).
Ataxia (1 paper, 2025). Ataxia refers to impaired coordination of voluntary muscle movement. "Taken together, we identified a novel interaction between MuSK and CaMK2β and at the same time, excluded defective MuSK kinase regulation as a possible cause of NMJ fragmentation in Mbnl1ΔE3/ΔE3 mice or ataxia in Camk2bΔE2/ΔE2 mice." (PMID 40295530, 2025). "Accordingly, we ruled out MuSK phosphorylation as the cause of synapse fragmentation in a mouse model for myotonic dystrophy type 1, in which the muscle-specific splice-variant of CaMK2β is missing, or as the cause of ataxia or delayed muscle development in CaMK2β knockout animals." (PMID 40295530, 2025).
Atrophy (1 paper, 2022). Any weakening or degeneration, especially through lack of use. "Additionally, muscle biopsies of patients with anti-MuSK-Abs MG show myopathic signs, whereas neurogenic features and atrophy are more frequently found in patients with anti-AChR-Abs-positive MG." (PMID 36712429, 2022).
cerebrovascular disease (1 paper, 2025). "Type b patients had higher MuSK+ prevalence and increased cardiovascular and cerebrovascular disease incidence rates than type a cases." (PMID 39968461, 2025). "Pronounced differences were found between types a and b with respect to MuSK+ (0 vs. 6.43%, p < 0.001) and coexisting cardiovascular and cerebrovascular diseases (8.57% vs. 15.79%, p = 0.013)." (PMID 39968461, 2025).
distal arthrogryposis (1 paper, 2018). A muscle tissue disease characterized by congenital joint contractures of hand and feet. "Expression of several genes linked to motor neuronopathy and familiar amyotrophic lateral sclerosis (EPHA4, IGHMBP2, VAPB, BICD2, and DYNC1H1) or distal arthrogryposis (MYH8, ZC4H2, MUSK, RAPSN) were significantly upregulated or downregulated." (PMID 29727687, 2018).
glioma (1 paper, 2023). A benign or malignant brain and spinal cord tumor that arises from glial cells (astrocytes, oligodendrocytes, ependymal cells). "MuSK-CAART cytotoxicity was subsequently evaluated against U87-MG glioma cells, which express MMP16 as well as LRP4." (PMID 36658341, 2023).
melanoma (1 paper, 2021). A malignant, usually aggressive tumor composed of atypical, neoplastic melanocytes. "Herein, we present the first case of anti-MUSK (+) MG in a woman with metastatic BRAF-mutant melanoma after long-term treatment with dabrafenib (BRAF inhibitor) and trametinib (MEK inhibitor)." (PMID 34722270, 2021).
muscular atrophy (1 paper, 2025). "The trophic signaling pathway converging on MuSK has been assumed to have therapeutic potential for a variety of diseases characterized by or associated with neuromuscular synaptic defects, especially to counteract muscular atrophy." (PMID 39898046, 2025).
Myotonia (1 paper, 2015). An involuntary and painless delay in the relaxation of skeletal muscle following contraction or electrical stimulation. "Further defining of the cause of the myotonia would likely offer a better understanding of the pathophysiology of MuSK Ab in MG." (PMID 26770848, 2015).
neuromyelitis optica (1 paper, 2023). A rare inflammatory disease of the central nervous system characterized mainly by attacks of uni- or bilateral optic neuritis (ON) and acute myelitis. "These antibodies can co-exist with anti-AChR or anti-MuSK antibodies and can be detected in other autoimmune diseases, such as neuromyelitis optica (NMO) and multiple sclerosis (MS)." (PMID 38140161, 2023).
neuromyotonia (1 paper, 2020). "Nevertheless, particular attention must be taken in the interpretation of electrophysiology results in cases of suspected MuSK-MG as misleading signs of denervation and neuromyotonia has been reported in the presence of MuSK antibodies." (PMID 32982689, 2020).
ovarian carcinoma (1 paper, 2024). A malignant neoplasm originating from the surface ovarian epithelium. "Moreover, other genes related to the neuromuscular junction like the MuSK activator Agrin, Membralin and SLC25A1 are expressed in SKOV3WT ovarian carcinoma cells and overexpressed in SKOV3 cells exposed to cisplatin." (PMID 39592661, 2024).
relapsing-remitting MS (1 paper, 2019). "Finally, in the neurologic [MS, NMOSD, OND] cohort, one relapsing-remitting MS (RRMS) patient, one NMOSD patient, and two HDs were positive for MOG autoantibodies; nine NMOSD patients were positive for AQP4 autoantibodies; and two HDs were positive for MuSK autoantibodies." (PMID 30824481, 2019).
thymolipoma (1 paper, 2016). "Here, we present a young woman with thymolipoma and MG (a very uncommon kind of tumor-associated MG) and high level of anti-MuSK-Ab." (PMID 32195208, 2016). "The presence of anti-MuSK Ab in a thymolipomatous (an uncommon tumor of thymus) MG is an atypical and new finding of MG because of not only thymolipoma but the presence of anti-MuSK antibodies which makes this case different from the previous reports of the antibodies-associated MG." (PMID 32195208, 2016).
neuromuscular disease (9 papers, 2014 to 2025). "We show here that recombinant antibodies, derived from MuSK MG patients, cause severe neuromuscular disease in mice." (PMID 39288173, 2024). "We show that a single injection of a recombinant, pathogenic antibody to MuSK, derived from a MuSK MG patient, triggers neuromuscular deficits in mice, which resemble neuromuscular disease in MuSK MG patients." (PMID 39288173, 2024). "On the other hand, MuSK levels may be normal in other neuromuscular diseases associated with neuromuscular synaptic deficits, such as SMA." (PMID 39898046, 2025). "This first proof of concept of a MuSK agonist in a clinically relevant MuSK MG model forms a starting point for therapeutic studies toward ARGX-119 efficacy in neuromuscular diseases." (PMID 39898046, 2025). "Our proposed method has predicted that erlotinib interacts with Muscle, skeletal, receptor tyrosine kinase (MuSK) which its antibodies are found in neuromuscular diseases." (PMID 31249365, 2019). "Future experiments will reveal if NT-1654 can be of benefit in the treatment of human neuromuscular diseases that directly or indirectly affect the agrin/Lrp4/MuSK pathway." (PMID 24520420, 2014). "Indeed, synaptic MuSK levels have been described to vary between muscles from different neuromuscular disease models." (PMID 39898046, 2025). "Moreover, increasing MuSK activity and retrograde signaling may also slow the deterioration of neuromuscular synapses in other neuromuscular diseases and during aging." (PMID 29460776, 2018). "Presumably, augmenting MuSK phosphorylation boosts poorly understood pathways that act downstream from MuSK to stabilize synapses that would otherwise deteriorate or disassemble, suggesting that ARGX-119 may provide therapeutic benefit for multiple neuromuscular diseases." (PMID 39288173, 2024).
cancer (7 papers, 2017 to 2026). A tumor composed of atypical neoplastic, often pleomorphic cells that invade other tissues. "Six patients were anti‐MuSK antibody positive, none of these had extrathymic cancer." (PMID 39829143, 2025). "Another patient was later found to have MuSK antibodies after a normal SFEMG, but did not receive any myasthenic therapy due to intercurrent cancer." (PMID 28592233, 2017).
tumor (6 papers, 2015 to 2025). "Activation of MuSK by Agrin enhances cell proliferation, promotes migration, and stimulates tumor growth." (PMID 29415504, 2018). "If this HCC tumor model reflects HCC in humans, these findings would suggest that MuSK signaling contributes to tumorigenesis." (PMID 29415504, 2018). "Importantly, overexpression of Lrp4 and MuSK in HCC tumours (8 out of 11 HCC patients) is consistent with the notion that Agrin functions through the Lrp4–MuSK complex to activate FAK in driving the oncogenic programme of HCC cells." (PMID 25630468, 2015).
myopathy (5 papers, 2017 to 2024). A disease of the muscle in which the muscle fibers do not function properly. "Both MuSK(+) and MuSK(−) patients, in contrast, have mild myopathy with frequent mitochondrial abnormalities." (PMID 38534400, 2024). "One possibility would be that reduced MUSK and dystrophin expression lead to remodeling of the muscle and adaptations of growth to compensate, but these changes ultimately lead to myopathy." (PMID 30820362, 2019). "The specificity of MuSK ELISA was 0.95 (95% CI 0.87–0.99) based on the results from 63 serum samples of disease control which consisted of 45 patients diagnosed with a disease other than MG in the initial cohort (MND 30, LEMS 5, Myopathy 4, Others 6) and 18 patients with RIPA-AChR Ab-positive MG." (PMID 36396811, 2023).
infection (2 papers, 2022 to 2025). The state of being infected such as from the introduction of a foreign agent such as serum, vaccine, antigenic substance or organism. "Crucially, we could not adequately account for critical variables such as MG autoantibody subtype (AChR, MuSK, LRP4), patient age, and specific immunosuppressive regimens-all of which are known to influence infection risks and therapeutic responses." (PMID 41322303, 2025).
neurological diseases (2 papers, 2015 to 2021). "In conclusion, it seems that the paradigm of the predominantly IgG4 MuSK and predominantly IgG1 AChR MG can be extrapolated to other autoimmune neurological (and non-neurological) disorders." (PMID 34220839, 2021). "The aim of this study was to test the presence and diagnostic significance of anti-LRP4 autoantibodies in an Italian population of 101 myasthenic patients (55 dSN, 23 AChR positive and 23 MuSK positive), 45 healthy blood donors and 40 patients with other neurological diseases as controls." (PMID 26284792, 2015).
psychiatric disorder (1 paper, 2024). A disorder characterized by behavioral and/or psychological abnormalities, often accompanied by physical symptoms. "Other findings included a significantly higher HADS-A score in gMG patients with psychiatric disorders versus gMG patients without such disorders, and similar HAM-A scores in patients with MuSK + MG and AChR + MG." (PMID 38336636, 2024). "Other findings included a significantly higher HADS-D score in gMG patients with psychiatric disorders versus gMG patients without such disorders, and similar HAM-D scores in patients with MuSK + MG and AChR + MG." (PMID 38336636, 2024).
MUSK also shares sentences with these, for which no sentence is quoted: pemphigus vulgaris (4 papers); chronic inflammatory demyelinating polyneuropathy (3); liver cancer (3); Cognitive impairment (2); Emery-Dreifuss muscular dystrophy (2); encephalitis (2); endometriosis (2); genetic disorders (2); Lambert-Eaton myasthenic syndrome (2); myotonic disorders (2); Parkinson disease (2); pemphigus (2); thrombotic thrombocytopenic purpura (2); Vocal cord paralysis (2); age (1); anemia (1); arthrogryposis (1); atrial fibrillation (1); autoimmune encephalitis (1); autoimmune pancreatitis (1); autoimmune thyroid disease (1); benign prostatic hyperplasia (1); Cachexia (1); channelopathies (1); chronic kidney disease (1); depression (1); diabetes mellitus (1); Encephalopathy (1); experimental autoimmune encephalomyelitis (1); External ophthalmoplegia (1).
A further 36 diseases each share a sentence with MUSK in 1 paper.